MIR933 (microRNA 933)
Synonyms: hsa-mir-933; MIRN933; mir-933
Gene: MicroRNA gene on chromosome 2 (175,167,633 to 175,167,709, reverse strand). Ensembl gene ENSG00000215973.
Homologues: Orthologues: chimpanzee ptr-mir-933 (100% identical).